METTL3 (methyltransferase 3, N6-adenosine-methyltransferase complex catalytic subunit)
Diseases named in the same sentence as METTL3 in open-access papers (continued):
Sharing a sentence is not in itself a finding about the gene and the disease.
gastric cancer (continued). "METTL3 was also over-expressed in pancreatic cancer, bladder cancer, glioma and gastric cancers, and promotes proliferation, invasion, and drug resistance of cancer cells." (PMID 33363011, 2020). "In recent years, the biological functions of METTL3 have been widely studied to be involved in various types of cancer development, including gastric cancer (GC), colorectal cancer (CRC), liver cancer (LC), and pancreatic cancer (PC)." (PMID 32429972, 2020). "The expression of METTL3 gradually increased with the progress of tumor stage and grade, but METTL3 knockdown inhibited cell proliferation, migration and invasion in human gastric cancer cells." (PMID 32201509, 2020). "In gastric cancer (GC), METTL3 can cause m6A to accumulate on HDGF mRNA, which indicates proliferation and poor prognosis and enhances the stability of zinc finger MYM-type containing 1 (ZMYM1) mRNA so that it accelerates epithelial-mesenchymal transition (EMT) and metastasis." (PMID 32303268, 2020). "The up-regulated METTL3 in gastric cancer was positively correlated with the poor prognosis of patients, and METTL3 promoted epithelial–mesenchymal transition of gastric cancer, leading to tumor invasion and metastasis." (PMID 33363011, 2020). "Here, we reported that frequent upregulation of METTL3 was responsible for the aberrant m6A levels in gastric carcinoma." (PMID 32175271, 2020). "For the first time, our study has revealed an oncogenic role for METTL3 in human gastric cancer in vitro." (PMID 30886897, 2019). "Taken together, these data suggest that down-regulation of METTL3 by shRNA transfection significantly inhibits cell proliferation and colony formation by human gastric cancer in vitro." (PMID 30886897, 2019). "In order to study the effect of METTL3 on human gastric cancer in vitro, a METTL3-targeted shRNA was designed and constructed." (PMID 30886897, 2019). "METTL3 and m6A were upregulated in human osteosarcoma, gastric cancer, melanoma, ovarian carcinoma, and hepatocellular carcinoma." (PMID 31921660, 2019). "In gastric cancer, up-regulated METTL3 promotes stability of ZMYM1, thus enhancing EMT process in vitro and metastasis in vivo." (PMID 31801551, 2019). "In order to determine the action mechanism of METTL3 in human gastric cancer, we investigated the effect of METTL3 knockdown on the AKT signaling pathway." (PMID 30886897, 2019). "Through using RNA interference, we found that METTL3 knockdown significantly inhibited cell proliferation, migration and invasion in the human gastric cancer cell lines AGS and MKN45." (PMID 30886897, 2019). "Here we knocked down METTL3 in human gastric cancer cell lines, AGS and MKN45, by using shRNA transfection." (PMID 30886897, 2019). "In this study, we investigated the function of METTL3 in human gastric cancer by using RNA interference technology." (PMID 30886897, 2019). "qRT-PCR and immunohistochemistry were used to evaluate the expression of methyltransferase-like 3 (METTL3) in gastric cancer (GC)." (PMID 31607270, 2019). "Mechanistic investigation suggested that METTL3 led to inactivation of the AKT signaling pathway in human gastric cancer cells, including decreased phosphorylation levels of AKT and expression of down-stream effectors p70S6K and Cyclin D1." (PMID 30886897, 2019). "In gastric cancer, up-regulated METTL3 enhances m6A methylation in HDGF and promotes the IGF2BP3-directed-stability of it, therefore facilitating cell proliferation and metastasis in vitro and in vivo." (PMID 31801551, 2019). "Therefore, miR-4429 inhibits the stabilization of SEC62 m6A by targeting Mettl3, thereby inhibiting the progression of gastric cancer." (PMID 41517663, 2026). "Later, miR-1269b was also found to be a miRNA that could inhibit gastric cancer cell proliferation, migration and invasion by downregulating Mettl3 expression." (PMID 41517663, 2026). "Research has found that overexpression of METTL3 promotes liver metastasis of gastric cancer (GC)." (PMID 40097750, 2025).
gastric cancer (continued). "Moreover, studies with oxaliplatin sensitive and resistant gastric cancer organoids revealed that CD133+ CSCs acquire resistance through METTL3-mediated m6A modification of PARP1 mRNA." (PMID 41228380, 2025). "For example, METTL3 promotes tumor progression in colorectal and gastric cancers 28,29." (PMID 39990672, 2025). "Interestingly, homeobox A10 (HOXA10) upregulation increases m6A levels and METTL3 expression in gastric cancer, possibly by promoting the TGFB2/SMAD pathway." (PMID 40986143, 2025). "In gastric cancer, upregulation of METTL3 is correlated with a poor prognosis for patients." (PMID 40356596, 2025). "Overall, METTL3 is a promising new therapeutic target for gastric cancer and may improve the efficacy of immunotherapy." (PMID 39678510, 2024). "While the significance of METTL3 inhibitors is unarguable, the methyltransferase activity of METTL3 appears to be dispensable for its translation role in specific cancers, such as lung and gastric cancer." (PMID 38444581, 2024). "Referring to studies of downstream targets regulated by METTL3 in tumours, it has been reported that in gastric cancer, METTL3 promotes ZMYM1 mRNA stability through m6A modification, subsequently enhancing its protein expression through the m6A reader protein HuR (also known as ELAVL1)." (PMID 38238831, 2024). "Therefore, METTL3 promotes oxaliplatin resistance in gastric cancer cells via the DNA damage repair process." (PMID 39678510, 2024). "Interestingly, cytoplasmic and catalytically inactive METTL3 was able to induce a global activation of translation and was sufficient to rescue the invasive and proliferative phenotype of gastric cancer cells upon knockdown of endogenous METTL3." (PMID 38444581, 2024). "Everolimus, as an mTOR inhibitor, reversed the METTL3-induced proliferation in a dose-dependent manner, which may be used in the treatment of m6A/METTL3-high gastric cancer." (PMID 39009956, 2024). "For instance, HOXA10 promotes gastric cancer EMT via the TGFB2/Smad/METTL3 signaling axis." (PMID 38178023, 2024). "Elevated METTL3 expression promoted tumor angiogenesis and glycolysis in gastric cancer." (PMID 37858219, 2023). "In addition, elevated expression of METTL3 was significantly associated with TNM stage and vessel invasion of tumors in gastric cancer patients." (PMID 38053093, 2023). "HBXIP promotes the progression of gastric cancer via METTL3-mediated MYC mRNA m6A modification." (PMID 36891150, 2023). "Although the involvement of METTL3 in DNA repair is still underexplored, our findings shed light on its significance and its potential in informing the development of novel therapies for gastric cancer." (PMID 37822880, 2023). "Furthermore, we found that DNA repair pathways were significantly activated in OXA-resistant Gastric cancer cells, and METTL3 knockdown significantly inhibited DNA repair pathways." (PMID 37822880, 2023). "One research reported that miR-4429 could inhibit METTL3 expression to play the role of suppressor in gastric cancer." (PMID 36875073, 2023). "Additionally, the overexpression of METTL3 and its oncogenic role has been revealed in various cancers such as gastric cancer, hepatocellular carcinoma, hepatoblastoma, colorectal cancer, bladder cancer and lung cancer." (PMID 37437245, 2023). "Overall, ANGPTL3 may be a useful biomarker in gastric cancer, and the combination of “writer” METTL3 and ANGPTL3 exhibits an innovative m6A-dependent regulatory mechanism." (PMID 37344779, 2023). "Consequently, targeting METTL3 holds great promise as a viable adjuvant strategy in the treatment of Gastric cancer patients." (PMID 37822880, 2023). "Consequently, we propose that METTL3 is potentially relevant to OXA resistance in gastric cancer patients, and its knockdown effectively mitigates this resistance." (PMID 37822880, 2023).
gastric cancer (continued). "Consistent with this, in gastric cancer, METTL3 enhances the stability of NDUFA4." (PMID 37996892, 2023). "Moreover, the overexpression of METTL3 promotes the proliferation and migration of gastric cancer cells." (PMID 37822880, 2023). "Here, our study reported that METTL3 governed the expression of PD-L1 in gastric cancer cells." (PMID 36003776, 2022). "However, in line with other studies, we found that METTL3 regulated the expression of PD-L1 in gastric cancer." (PMID 36003776, 2022). "Furthermore, miR-4429 or silencing SEC62 blocked tumor cell proliferation and facilitated apoptosis, suggesting that miR-4429 and its downstream gene METTL3 are potential targets for gastric cancer prevention and management." (PMID 35090469, 2022). "In addition, the knockdown of DEK was found to reverse the effects of METTL3 on the proliferation and migration ability of gastric cancer cells, which was further verified by a lung metastasis model at the animal level." (PMID 35742899, 2022). "METTL3 also promoted liver metastasis in a mouse model of gastric cancer." (PMID 36008936, 2022). "Moreover, the regulatory effect of METTL3 is prevalent in other types of cancers, including glioma, gastric cancer, hepatocellular carcinoma (HCC), breast cancer (BRCA), and acute myeloid leukemia (AML)." (PMID 35804965, 2022). "Consistent with our results, it has been demonstrated that METTL3 is upregulated in cancer tissues compared with the adjacent normal tissues in human breast cancer and gastric cancer, and it also can be used as a candidate target for individualized treatments against these malignancies." (PMID 36058919, 2022). "In addition, MYC has been identified as a target of METTL3 in acute myeloid leukemia, gastric cancer, prostate cancer, and OSCC." (PMID 36429032, 2022). "For example, METTL3 facilitates cell proliferation and metastasis in gastric cancer." (PMID 35255776, 2022). "In addition, the expression of METTL3 in gastric cancer cells can also affect the carcinogenic function of tumor cells, and its overexpression can promote tumor progression." (PMID 35022030, 2022). "Moreover, METTL3 regulates the m6A modification of SPHK2 to promote the progression of gastric cancer." (PMID 35012593, 2022). "METTL3-high tumors showed more sensitivity to everolimus, a rapamycin analog, in gastric cancer." (PMID 36058934, 2022). "Compared with normal cells, METTL3 increased in gastric cancer cells." (PMID 35090469, 2022). "In NSCLC and gastric cancer, METTL3 promoted migration through downstream activation of PI3K/AKT; however, whether this mechanism is m6A-dependent is unclear." (PMID 35350378, 2022). "Moreover, overexpression of METTL3 increased the expression levels of PD-L1 in gastric cancer cells." (PMID 36003776, 2022). "However, the specific mechanism of METTL3 in the proliferation and metastasis of gastric cancer is still unclear." (PMID 34394353, 2021). "Therefore, Yes-associated protein 1 (YAP1) in the Hippo pathway was selected as the target, and the relationship between METTL3 and the proliferation and metastasis of gastric cancer was proved through a series of experiments." (PMID 34394353, 2021). "Moreover, upstream regulatory molecules of METTL3 in gastric cancer have also been discovered and confirmed in lots of researches in recent years." (PMID 33976730, 2021). "METTL3 has been shown to promote the proliferation and mobility of gastric cancer cells." (PMID 34395102, 2021). "Wang Qiang and others found that the expression of METL3 promotes tumor angiogenesis and glycolysis in gastric cancer, and Mettl3 may be a cancer-promoting factor for gastric cancer." (PMID 34187307, 2021). "Consistently, our study also verified the oncogenic role of METTL3 in gastric cancer." (PMID 33976730, 2021). "This study analyzed whether the downstream component of the Hippo signaling pathway, YAP1, was involved in human gastric cancer to explore the mechanisms of METTL3-silencing-mediated tumor inhibition." (PMID 34394353, 2021).
gastric cancer (continued). "As METTL3 was the primary regulator involved in the abundant m6A RNA modification, the relations between lncRNAs and m6A modification have also emerged as research hotspots in the initiation and progression of gastric cancer." (PMID 33976730, 2021). "EMT process was facilitated by stable ZMYM1 through up-regulation of METTL3 in gastric cancer." (PMID 34116604, 2021). "METTL3 has a role in gastric cancer cells’ proliferation and migration regulation, which significantly affects the expression of α-smooth muscle actin, and is expected to become gastric cancer’s target in future." (PMID 34476213, 2021). "METTL3-mediated m6A modification facilitates gastric cancer progression and has poor prognosis." (PMID 34277622, 2021). "Besides, our subsequent experiments have suggested that BLACAT2 promotes gastric cancer proliferation, migration, and invasion but inhibits apoptosis by regulating the miR-193b-5p/ METTL3 axis." (PMID 33976730, 2021). "N6-methyladenosine (m6A) methyltransferase 3 (METTL3) may be involved in the proliferation and metastasis of gastric cancer." (PMID 34394353, 2021). "Studies have found that in gastric cancer, the expression of METTL3 is elevated." (PMID 35070987, 2021). "As for gastric cancer, studies confirmed that METTL3 is a vital tumor promoter." (PMID 33976730, 2021). "Therefore, immunoblotting experiments were conducted, revealing that the level of METTL3 protein was significantly higher in gastric cancer tissues than in adjacent tissues." (PMID 34394353, 2021). "Perhaps, combination of HDACi and METTL3 inhibitors may become the feasible approach to interrupt the progression of gastric cancer." (PMID 33754077, 2021). "Additionally, rescue assays demonstrated that BLACAT2 exerts oncogenic roles, which rely on the expression of METTL3 in gastric cancer." (PMID 33976730, 2021). "Furthermore, in bladder cancer, gastric cancer, and colorectal cancer, increased expression of METTL3 correlated with poor prognosis." (PMID 34616742, 2021). "In gastric cancer, LINC00470 associates with METTL3 to weaken the stabilization of PTEN mRNA." (PMID 34722298, 2021). "METTL3 has been reported to promote gastric cancer angiogenesis by secreting HDGF." (PMID 32211315, 2020). "In gastric cancer cells, H3K27ac can activate Mettl3 transcription to increase its expression." (PMID 32444598, 2020). "In this study, we found elevated levels of m6A and METTL3 in gastric cancer." (PMID 33037176, 2020). "To investigate the biological role of METTL3 in gastric cancer, we established METTL3-downregulated and -upregulated cells using lentivirus containing shRNA and plasmids containing METTL3, respectively." (PMID 33037176, 2020). "In conclusion, METTL3/m6A promotes gastric cancer growth and metastasis by facilitating pri-miR-17-92 processing into the oncogenic miRNA cluster and activating the AKT/mTOR pathway by targeting PTEN and TMEM127, which could be targeted by everolimus." (PMID 33037176, 2020). "For example, METTL3-mediated m6A methylation enhanced ZMYM1 mRNA expression in gastric cancer." (PMID 33251217, 2020). "METTL3 has been reported as an important player in gastric cancer development." (PMID 33372610, 2020). "METTL3 may play a carcinogenic role in lung cancer, bladder cancer, gastric cancer, osteosarcoma, cutaneous squamous cell carcinoma, and acute myeloid leukemia (AML)." (PMID 32111180, 2020). "For example, miR-4429 obstructs gastric cancer progression by binding with METTL3." (PMID 32469064, 2020). "METTL3 promotes the development of colorectal cancer, gastric cancer, bladder cancer, breast cancer, renal cell carcinoma, and pancreatic cancer cells, and the occurrence of non-small cell lung cancer is related to METTL3." (PMID 33237039, 2020). "Moreover, another two groups also found that METTL3 promoted the proliferation and mobility of gastric cancer cells." (PMID 33372610, 2020).
gastric cancer (continued). "Moreover, METTL3 knockdown decreased Bcl2 and increased Bax and active Caspase-3 in gastric cancer cells, which suggested the apoptotic pathway was activated." (PMID 30886897, 2019). "Moreover, western blot results also confirmed the effectiveness of RNA interference Sequentially, we analyzed the impact of METTL3 knockdown on the proliferation of gastric cancer cells." (PMID 30886897, 2019). "Wound closure of shMETTL3 transfected cells was significantly inhibited compared to NC group in both AGS and MKN45 cells at 24 h and 48 h, suggesting that down-regulation of METTL3 could inhibit cell migration of gastric cancer." (PMID 30886897, 2019). "In order to test whether METTL3 was involved in migration and invasion of human gastric cancer cells, a scratch assay and a transwell assay were performed." (PMID 30886897, 2019). "Our results suggest that METTL3 may be a potential therapeutic target for the treatment of human gastric cancer." (PMID 30886897, 2019). "In addition, the influence of METTL3 knockdown on colony formation of human gastric cancer was also investigated." (PMID 30886897, 2019). "Moreover, METTL3 has been shown to promote angiogenesis in gastric cancer." (PMID 38331776, 2024). "Additionally, METTL3 could promote angiogenesis and metastasis in gastric cancer (GC) and bladder cancer through regulating m6A and mRNA stability of hepatoma-derived growth factor (HDGF), tyrosine kinase endothelial (TEK) and VEGFA, respectively." (PMID 38322265, 2024). "In gastric cancer (GC), the previous studies confirmed in accordance that METTL3 augmented the resistance to platinum drugs." (PMID 36810281, 2023). "In addition, miR-4429 directly targets and inhibits METTL3, regulating gastric cancer progression." (PMID 37781524, 2023). "Moreover, a decrease in the migrationand proliferation of gastric cancer cells is also observed due tothe inactivation of the AKT pathway as a consequence of METTL3 downregulation;this also leads to lower levels of p70S6K and cyclin D1, which usuallysupport cell motility and replication." (PMID 36692498, 2023). "In gastric cancer (GC) cells, the activation of METTL3 transcription is induced by the promotion of the P300-mediated H3K27 acetylation of its promoter." (PMID 38201270, 2023). "As an important m6A regulator enzyme, the methyltransferase, METTL3, can promote tumor progression by regulating downstream target genes in leukemia, colorectal cancer, bladder cancer, and gastric cancer; however, the relationship between the m6A writer, METTL3, and VM formation remains unclear." (PMID 35595748, 2022). "In gastric cancer (GC), METTL3 promotes cell proliferation and liver metastasis in GC by enhancing m6A modification and stability of HDGF." (PMID 36008805, 2022). "Our finding suggests that METTL3 could regulate the expression of PD-L1 in gastric cancer cells." (PMID 36003776, 2022). "Similarly, previous bioinformatic analysis from databases like TCGA, GEO and HPA, supported that high expression of METTL3 was correlated with unfavorable prognosis in various cancers, including gastric cancer, colorectal cancer, liver cancer, prostate cancer and glioma." (PMID 36347025, 2022). "However, the mechanism of METTL3 in the development of gastric cancer is still inconclusive." (PMID 35742899, 2022). "In addition, this study further found that the inhibition of the expression of the YAP1 signaling pathway by peptide 17 in vitro and nude mice tumor formation models also eliminated the promoting effect of METTL3 on the proliferation and metastasis of gastric cancer cells." (PMID 34394353, 2021). "Conversely, METTL3 knockdown could active caspase-3 in gastric cancer cells." (PMID 32294948, 2020). "In addition, METTL3 expression was also elevated in four cases of gastric carcinoma tissues." (PMID 32175271, 2020).